CXCR4 (C-X-C motif chemokine receptor 4)
Diseases named in the same sentence as CXCR4 in open-access papers (continued):
Sharing a sentence is not in itself a finding about the gene and the disease.
tumor (continued). "Although CXCL12 promoted the proliferation index in vitro, and AMD3100 suppressed the proliferation index in vitro, as well as the tumor size in vivo, our study did not disclose whether the CXCL12/CXCR4 axis is responsible for ESCC survival or apoptosis." (PMID 27439769, 2016). "However, thus far, few studies have attempted to identify the linkage of intracellular AFP with tumor invasion and metastasis, and the intrinsic mechanisms involving the correlation between AFP and CXCR4 have never been investigated." (PMID 25815363, 2015). "No significant increase in expression of CXCR4 and uPAR in CK19+/VIM− CTC-enriched blood fraction would speak for the passive model of dissemination, in which tumor cells are physically translocated into the vasculature (or the neovasculature formed around tumor cells)." (PMID 24709997, 2014). "Further interestingly, CXCL12, the ligand of CXCR4, is highly expressed in the surrounding pancreatic tissue of the PDAC tumor (data not shown) and may lure cells out of the tumor for invasion or further dissemination." (PMID 24069258, 2013). "Because both the 2F7 cell line and Namalwa cell lines are similar in that they are EBV(+) BL cell lines, we initially studied CXCR4/CXCL12 in our model, but found no indications that these molecules were important in promoting tumor growth in this model (unpublished results)." (PMID 23936541, 2013). "Nevertheless, it has to be kept in mind that gene transcription does not always correlate with mRNA translation and that the tumour biological effect of CXCL12 may also depend on the presence and histoanatomical distribution of CXCR4." (PMID 20386750, 2010). "Only when these stromal sects are detected, immunoreactivity for CXCL-12 is associated to the stromal cells and this is not greatly different in control or PICP treated tumor, leading us to suggest that all the effects of PICP we have detected are independent from CXCR4/CXCL-12 signaling." (PMID 19226458, 2009). "Furthermore, CXCR4 and CXCR7 were highly expressed in tumoural blood vessels whereas no staining was observed in the endothelium of blood vessels in normal pancreatic tissue." (PMID 19352387, 2009). "However, the CXCR4 and CCR5 ligands were more uniformly expressed in tumor and nontumor tissues." (PMID 35954489, 2022). "The incorporation of CXCR4 led to specific chemotaxis to CXCL12/SDF-1α-expressing GBM U87MG cells, in addition to significantly increasing the survival and even leading to complete remission of tumor xenografts in mice, in comparison to CAR-NK cells without CXCR4 co-expression." (PMID 35203609, 2022). "More importantly, CXCR4 staining in the same preparations showed co-localization with CD31 staining with similar intensity for both SuDHL8 and U2932, indicating that the marked differences of CXCR4 expression in the tumor cells are not reflected in the respective tumor vasculatures." (PMID 34793563, 2021). "Furthermore, we found that as few as ten ALDH+CD44+CXCR4+CD24+-PCa cells, but not other subsets, could develop a palpable tumour within 100 days of implantation." (PMID 34247196, 2021). "This drastic change of NK cell number was not attributable to changes of CXCR4 and CXCR3 ligand expression levels since CXCL10 expression in the BM was not modulated by NK cell transfer or IL-15 administration, nor was the expression of CXCL10 and CXCL12 by BM tumor cells." (PMID 31699153, 2019). "Depending on different tumor types, CXCR7 may or may not co-express with CXCR4." (PMID 29977203, 2018). "Here we have observed membrane and nuclear CXCR4 reactivity in CEOT cells regardless of tumor topography (tumor center versus the advancing edge), suggesting the involvement of this chemokine in mediating locally tumor cell invasion or even a potential malignant evolution of this tumor." (PMID 27871286, 2016).
tumor (continued). "Collectively, these results indicate that effector B cells directly kill tumor cells in cell-cell contact via the Fas/FasL and CXCR4/CXCL12 pathways as well as perforin, while without cell contact, perforin secreted by B cells could also lead to tumor cell cytotoxicity." (PMID 27528023, 2016). "According to our results, if decreased CXCR4 and HER-2 expressions are present in a tumor, treatment could be continued, whereas absence of change or increased CXCR4 and HER-2 expressions would imply that patients should be treated with another chemotherapeutic regimen." (PMID 23046610, 2012). "Furthermore, in hypoxic tumours with positive CA9 expression, a higher proportion of Treg was positive for CXCR4 (median = 18.1%, interquartile range = 9.7% to 40.3%) compared to CA9 negative tumours (median = 4.3%, interquartile range = 2.1% to 19.9%) (P = 0.049)." (PMID 21521526, 2011). "We show here that CXCR4 overexpression in non-metastatic CXCR4-negative NB cells IGR-NB8 and in moderately metastatic, CXCR4 expressing NB cells IGR-N91, strongly increased tumour growth of primary tumours and liver metastases, without altering the frequency or the pattern of metastasis." (PMID 17925864, 2007). "However, in MM cells engagement of CXCR4 by BoxA does not promote cell growth but rather induces the surface exposure of calreticulin and the depletion of surface CD47, tilting the balance of “eat me” and “don’t eat me” signals, and promoting tumor cell phagocytosis by macrophages." (PMID 33956406, 2021).
cancer (1,994 papers, 2002 to 2026). A tumor composed of atypical neoplastic, often pleomorphic cells that invade other tissues. "Despite its recognized potential as a cancer biomarker, the presence of CXCR4 on EVs remains underexplored for diagnostic purposes." (PMID 41892066, 2026). "CXCR4 is an appealing target for diagnostic and therapeutic approaches in cancer patients and has shown promise in hematological malignancies." (PMID 40075611, 2025). "Beyond its prognostic and diagnostic uses, the increase of CXCR4 expression is a critical driver of therapy resistance by regulating DNA damage repair, cancer stemness, and immune evasion, all of which impair response to chemotherapy, radiotherapy, and ICIs." (PMID 41383468, 2025). "Despite CXCR4’s broad expression profile, its overexpression in certain cancers is attributed to CSCs and is linked to poor outcomes." (PMID 39753364, 2025). "The CXCL12/CXCR4 axis has been implicated in the regulation of cancer cell proliferation, invasion, angiogenesis, and metastasis in several types of cancers, including GC." (PMID 40481962, 2025). "In contrast, the CXCL12/CXCR4 axis, widely implicated across multiple cancer types, drives PI3K/AKT and PI3K/AKT/mTOR signaling, macrophage recruitment, and metastatic spread, particularly to the liver." (PMID 40943634, 2025). "As the disease advanced, Fib_FBLN1+ fibroblasts—associated with tissue repair and homeostasis gradually transitioned into cancer-associated fibroblasts (CAFs), including Fib_POSTN+, Fib_CD74+, and Fib_CXCR4+ subpopulations." (PMID 40948762, 2025). "Single-cell transcriptomic analysis revealed that CXCR4 expression in breast-infiltrating carcinomas is primarily associated with immune cells, although it is also present in malignant cells." (PMID 40362664, 2025). "CXC chemokine receptor 4 (CXCR4) is associated with the progression and metastasis of numerous malignant tumors." (PMID 38524630, 2024). "The expression of CXCR4 is associated with increased invasiveness and distant metastases in several cancers." (PMID 39070795, 2024). "Several pathological processes, such as cancer and inflammatory diseases, are implicated in aberrant CXCR4/CXCL12 signaling." (PMID 39070795, 2024). "In other cancer, there are also many studies confirmed that high expression of CXCR4 is associated with poor prognosis of patients." (PMID 38524630, 2024). "CXCR4 has been studied in practically all the different types of cancer because its expression is independently associated with decreased survival." (PMID 38791878, 2024). "Previous studies indicate that antagonists against CXCR4 have shown enormous potential as cancer diagnostic and therapeutic agents." (PMID 38982161, 2024). "High CXCR4 expression has been associated with poor prognosis in several malignant tumors including mesenchymal neoplasms." (PMID 38893721, 2024). "CXCR4 is associated with the occurrence, progression, invasion, and metastasis of a variety of malignant tumors according to previous literatures." (PMID 38524630, 2024). "Fifth, previous studies suggested possible associations between the SDF-1α/CXCR4 axis and development of various clinical conditions such as immunological diseases and cancers." (PMID 38555431, 2024). "The server showed that all the mutations were clustered in 7 distinct sections, Remarkably, it was also noted that the protein encoded by CXCR4 is encompassed within the set of known cancer-associated genes." (PMID 39715225, 2024). "CXCR4 has been previously implicated in the growth and metastasis of various cancers, including SCLC." (PMID 36597126, 2023). "One such target is CXCR4, a gene encoding the C-X-C chemokine receptor type 4 (CXCR4) protein, which plays an essential role in the metastasis of cancer cells." (PMID 38655233, 2023). "In general, enhanced CXCR4 expression seems to be associated with a worse prognosis for patients suffering from cancer." (PMID 36672341, 2023).
cancer (continued). "Intraperitoneal delivery of CXCR4-antagonist-armed oncolytic vaccinia virus led to nearly complete depletion of cancer-associated fibroblasts, M1 polarization of macrophages, and generation of SV40 T antigen-specific CD8+ T cells in transgenic mice." (PMID 36875325, 2023). "Overexpression of CXCR4 is associated with poor prognosis in various cancers such as breast, lung, and colorectal cancers." (PMID 36732336, 2023). "In literature, many studies have shown that CXCR4 expression is linked to cancer progression and metastases in hematopoietic as well as in various non-hematopoietic malignancies." (PMID 35397601, 2022). "Functionalized EVs demonstrated increased accumulation in target cells expressing common cancer associated markers such as CXCR4, EGFR and EpCAM both in vitro and in vivo." (PMID 35547755, 2022). "Recent cancer genome deep sequencing efforts have also revealed a higher frequency of mutations in CXCR4 in some tumor types, such as diffuse large B-cell lymphoma, uterine corpus endometrial carcinoma, and skin cutaneous melanoma." (PMID 34973340, 2022). "Chemokine receptors such as CXCR3 and CXCR4 have been shown to be upregulated in animal models of different types of cancer and have been strongly associated with SLN metastasis." (PMID 36266717, 2022). "Overexpression of CXC chemokine receptor 4 (CXCR4) is observed in many types of cancer and is associated with a poor prognosis." (PMID 36012588, 2022). "C-X-C Motif Chemokine Receptor (CXCR4) is an oncogene that widely studied and associated with worse clinicopathological features and prognosis outcome on many types of cancer." (PMID 36816176, 2022). "The chemokine receptor CXCR4 has been heavily implicated in the spread and mobility of many solid cancers based on its role in cancer cell chemotaxis as well as increased metastatic potential." (PMID 35259193, 2022). "The dual action of the beta-2 adrenergic receptor and the CXCR4 complex modulates G-coupled signaling involved in hematopoietic stem cell trafficking, such as that associated with cancer stem cell invasion." (PMID 35259193, 2022). "CXCR4 overexpression is associated with a poor prognosis in several cancers, whereas its inhibition prevents metastases." (PMID 35884987, 2022). "CXCR4 is a G protein-coupled receptor whose overexpression is associated with the onset or exacerbation of many human cancers." (PMID 35547755, 2022). "CXC chemokine-12 (CXCL12) can specifically bind to CXC chemokine receptor 4 (CXCR4) and is closely associated with the progression of cancer via multiple signaling pathways." (PMID 35893797, 2022). "Classically, CXCL12 recruits stromal cells in the lungs under normal conditions, and CXCR4 has been implicated in more than 20 human cancers." (PMID 35743888, 2022). "Several studies demonstrated that high CXCR4 expression has been linked to cancer progression and metastases in hematopoietic as well as in various non-hematopoietic malignancies." (PMID 35397601, 2022). "The expression of chemokine (C-X-C motif) receptor 4(CXCR4) in cancer cells is associated with increased expression of chemokine ligand CXCL12 in LSECs’ microenvironment and CXCR4-CXCL12 signaling drives metastasis." (PMID 36387238, 2022). "Changes in CXCR4 expression have been linked to the progression and metastases of several cancers, including B-NHL." (PMID 35805197, 2022). "In our study, we observed that a high ratio of pCXCR4/CXCR4 TIC in primary cancer cases was associated with a better RFS, especially during the early follow-up phase (first 2 years)." (PMID 35397601, 2022). "The chemokine receptor 4 (CXCR4) is a promising diagnostic and therapeutic target for the management of various cancers." (PMID 35336029, 2022). "By determining the cancer cell fraction (CCF) of CXCR4 mutations in WM the mutation S338X was identified as mostly sub-clonal with variable clonal distribution, which points to the mutation as a late oncogenic event acquired after MYD88 mutation." (PMID 33273682, 2021).
cancer (continued). "Multiple studies have shown that the overexpression of CXCR4 is observed in cancers and is associated with cell migration and invasion." (PMID 35053027, 2021). "In many different forms of cancer, CXCR4 is often overexpressed or overactivated, which is linked to cancer progression by promoting proliferation, survival, and metastasis." (PMID 34552197, 2021). "This was in line with previous findings that CXCR4 was positively associated with cancer‐related deaths." (PMID 34170080, 2021). "Overexpression of CXCR4 has been associated with poor outcomes in patients with advanced cancer, including breast, head and neck, ovarian, and non-small cell lung cancer (NSCLC), among others." (PMID 33507926, 2021). "CXCR4 has been associated with cancerogenesis for a long time: elevated CXCR4 expression levels have been portrayed in numerous cancers with relation to poor prognosis and therapy resistance." (PMID 33273682, 2021). "CXCR4 was suggested to have a critical role in liver metastasis of CRC cells by driving the transformation of hepatic stellate cells to cancer-associated fibroblasts (CAF) via CXCR4/SDF-1/TGF-β1 intercellular signalling." (PMID 34335790, 2021). "Several studies have shown that in MM, CXCR4 is aberrantly activated and associated with the progression, spread and relapse of the cancer." (PMID 34071917, 2021). "Of note, the CXCL12-binding receptor Ackr3 (encoding CXCR7), which is known to form heterodimers with CXCR4 and is dysregulated in inflammatory diseases and cancers, was upregulated." (PMID 34363012, 2021). "Accordingly, activity-optimized synthetic derivatives of EPI-X4 are promising leads for the therapy of CXCR4-linked disorders such as cancer or inflammatory diseases." (PMID 34552197, 2021). "Although previous data suggested that aberrant expressions or mutations of CXCR4 are relevant to cancer development, but the detailed regulating mechanisms have not been elucidated." (PMID 34180759, 2021). "In this study, we show that CXCL12 from TAMs exerts a paracrine effect on cancer cells via CXCR-4 and protects cancer cells from damage caused by docetaxel." (PMID 34069563, 2021). "Infiltration of pDCs into cancer tissues is associated with poor prognosis correlating with BC lymph node metastasis, with participation of the CXCR4/CXCL12 chemokine axis or stromal cell-derived factor 1 alpha (SDF-1α)." (PMID 34337083, 2021). "Early studies found that C‐X‐C chemokine receptor type 4 (CXCR4) is overexpressed in many cancers, and that high expression of CXCR4 is always associated with early metastasis and poor prognosis." (PMID 34449964, 2021). "These cancer cells are relevant clinical targets since CXCR4 overexpression is associated with aggressiveness and dissemination in many solid and hematological cancers 17-21." (PMID 32373205, 2020). "Regarding labeled nanoparticles, both T22-GFP-H6-ATTO and T22-GFP-H6-S-Cy5, present similar receptor specificity in cell culture and similar loss of targeting capacity in both human CXCR4+ cancer mouse models in vivo." (PMID 33105866, 2020). "Signaling pathways underlying communication of cancer metastatic cells with microglia are similar to the ones operating in peripheral metastases and include Wnt/β‐catenin signaling, CXCR4 and its ligand SDF1 and PI3K pathway." (PMID 32194848, 2020). "CXCL12/CXCR4 interaction can also induce activation of the canonical Wnt pathway that plays a key role in iCCA growth, metastasis and cancer susceptibility." (PMID 32784743, 2020). "Particularly, CXCR2 and CXCR4 are chemokine receptors for T-cells implicated in cancer invasion and metastasis." (PMID 32719800, 2020). "A vast body of literature associates the chemokine receptor CXCR4 with the development of cancer pathogenesis in humans, mice and zebrafish." (PMID 32161595, 2020).